DMRTC1B (DMRT like family C1B)
Tractability: No criterion of Open Targets' tractability assessment is met for any kind of drug.
Gene: Protein-coding gene on chromosome X (72,776,890 to 72,848,803, forward strand). Ensembl gene ENSG00000184911.
Subcellular location (Human Protein Atlas): Nucleoplasm; Intermediate filaments
Gene Ontology:
Molecular function: DNA-binding transcription factor activity, RNA polymerase II-specific; RNA polymerase II cis-regulatory region sequence-specific DNA binding
Biological process: regulation of DNA-templated transcription
Cellular component: chromatin; nucleus
Homologues: Orthologues: chimpanzee DMRTC1B (100% identical), macaque DMRTC1B (97% identical), Caenorhabditis elegans dmd-7 (16% identical), Caenorhabditis elegans dmd-4 (14% identical), Drosophila melanogaster dmrt99B (13% identical), Caenorhabditis elegans dmd-9 (10% identical), Caenorhabditis elegans dmd-5 (8% identical). Paralogues in human: DMRTC1 (100% identical), DMRTC2 (51% identical), DMRTA1 (21% identical), DMRTA2 (21% identical), DMRT3 (20% identical), DMRT2 (15% identical), DMRT1 (15% identical), DMRTB1 (11% identical).